MTOR (mechanistic target of rapamycin kinase)
Diseases named in the same sentence as MTOR in open-access papers (continued):
Sharing a sentence is not in itself a finding about the gene and the disease.
viral infection (continued). "Activated by costimulatory molecule ICOS, mTOR acts to drive glycolysis and lipogenesis and subsequently promotes Tfh cell responses during acute viral infection." (PMID 30828337, 2019). "Numerous studies discuss and show promising results targets for NSAIDs, mTOR pathway regulators, and FASN inhibitors in viral infection associated cancers but additional in vivo studies need to be done to fully exploit these pathways." (PMID 30717356, 2019). "A similar dependence of PD-L1 translation on PI3K/AKT/mTOR activity was also observed during viral infections." (PMID 29296193, 2017). "To further investigate the mechanistic action of the PI3K/mTOR signaling pathway in viral infection, we measured mTORC1 activation by monitoring the phosphorylation status of ribosomal protein S6 (pS6), a down-stream target of the mTORC1-mediated pathway." (PMID 28634408, 2017). "The activity of the transcription factor FOXO1 has been shown to increase upon mTOR inhibition during chronic viral infections and increased expression of co-inhibitory receptors such as PD-1." (PMID 29228684, 2017). "Cap-dependent translation is initiated by activation of the mammalian target of rapamycin (TOR; mTOR) that phosphorylates eIF4E-BP in response to extracellular stimuli in such viral infections." (PMID 28930151, 2017). "Some studies have reported that the phosphorylation of mTOR and Bad regulate cell survival and effect virus infection." (PMID 27560518, 2016). "Wnt signaling pathway (ko04310), TGF-beta signaling pathway (ko04350), and mTOR signaling pathway (ko04150) were also among the enriched pathways of the target genes, reflecting complicated biological events induced by virus infection." (PMID 27843944, 2016). "Viral infection is a significant stress that can activate, reduce or even suppress the mTOR signaling pathway." (PMID 27231932, 2016). "Despite viral infection inhibiting mTOR, a metabolic sensor controls cap-dependent translation, viral proteins are efficiently translated." (PMID 26317997, 2015). "To translate the importance of PI3K–mTOR pathway for NK cell functions during virus infection, we treated mice with rapamycin to block mTOR kinase activity downstream of PI3K." (PMID 26257729, 2015). "Consistent with our in vitro data, mice pre-treated with TORISEL had higher viral titers in both the skin (injection site) and muscle as compared to control mice, indicating that mTOR inhibition affects in vivo viral infection." (PMID 26317997, 2015). "As a master sensor of cellular homeostatic perturbations, several studies have investigated the relationship between mTOR activity and viral infection." (PMID 26317997, 2015). "Inhibition of mTOR allowed for the differentiation of Tfh cells in the absence of TGF-βR signaling, suggesting that TGF-β insulates Tfh progenitor cells from IL-2-delivered mTOR signals, thereby promoting Tfh differentiation during acute viral infection." (PMID 25569154, 2015). "The NK cell proliferation, cytokine production, and cytotoxicity are dependent on the metabolic induction of mTOR pathway during virus infection." (PMID 26257729, 2015). "The boosting of T-cell memory with mTOR inhibition has substantial therapeutic implications regarding the problems of viral infection and post-transplant malignancy in organ transplant recipients." (PMID 24565200, 2013). "We show that phosphorylation of Akt, FOXO and mTOR in CD8 T cells occurs in a dynamic fashion in vivo during an acute viral infection." (PMID 22359505, 2012). "Under various physiological and pathological conditions including cell development and differentiation, starvation, hypoxia, and virus infection, the highly conserved protein kinase mammalian target of rapamycin (mTOR) is inhibited, and autophagy is thus induced to maintain cellular homeostasis." (PMID 39789633, 2025).
viral infection (continued). "Some drugs, such as rapamycin, capivasertib, and bafilomycin, disrupt the activity of the mTOR signaling pathway and effectively inhibit viral infection and replication, suggesting that mTOR-related molecules are potential targets for anti-orthoflavivirus drug development." (PMID 40270809, 2025). "The most enriched biological processes for the proteins with increased abundance in AdV-EVs included the GO terms representative of protein translation in response to viral infections, cytoskeletal remodeling, interactions with the extracellular matrix, and mTOR and ErbB2 signaling pathways." (PMID 41157572, 2025). "The mTOR and NF-κB pathways seem closely related to viral infection." (PMID 39000284, 2024). "The induction of mTOR signaling has been reported to occur in viral infections." (PMID 39845048, 2024). "Currently, systemic MTOR inhibitors are used clinically to treat conditions with augmented MTOR signaling, from preventing organ transplant rejection to treating viral infection and cancer; however, this study underscores the importance of protecting vascular integrity in MTOR-inhibited conditions." (PMID 39510184, 2024). "When viral infection stimulates autophagy, the mammalian target of rapamycin (mTOR) is inhibited." (PMID 39227990, 2024). "The mTOR signaling pathway was significantly enriched in the 10 °C virus infection group, which may be the reason for the high mortality rate of flounder at 10 °C." (PMID 37627029, 2023). "Nutrients and the highly conserved nutrient-responsive Target of Rapamycin (TOR) signaling are also key factors in other somatic stress responses (such as viral infection), as mTOR activation can promote natural killer cell effector function to destroy virus-infected cells." (PMID 37989752, 2023). "Additionally, Slfn5, with shared DRE sites between IBP and viral infections, inhibited apoptosis by regulating the mTOR pathway." (PMID 37081881, 2023). "mTOR signaling pathway is also significantly enriched, and cellular responses to viral infection are influenced by the rapamycin complex 1 (mTORC1), a mechanistic target of the mTOR that drives viral proliferation and survival by regulating anabolic and catabolic processes." (PMID 37627029, 2023). "A study conducted on patients with EBV infection demonstrated upregulation of the PI3K/Akt/mTOR pathway, which has been reported in other viral infections and could indicate a general response to viral infection." (PMID 36742317, 2023). "Thus, we next examined if mTOR is required for PD-1 blockade–mediated induction of effector-like transitory CD8+ T cells during chronic viral infection." (PMID 36378537, 2023). "Since the appearance in the late 1990s of mTOR inhibitors (mTORi), these unmet needs in immunosuppression management could be addressed thanks to their benefits (reduced rate of viral infections and cancer)." (PMID 35887051, 2022). "Notwithstanding, another recent study has indicated that the decreased level of mTOR during early virus infection (4–6 hpi) could stimulate the autophagic pathway and help in the replication of RV." (PMID 35516441, 2022). "Inhibitors of mTOR block critical pathways to produce antiviral, anti-inflammatory, antiproliferative and other effects, and they have been applied to research in cancer, inflammation, central nervous system diseases and viral infections." (PMID 36014530, 2022). "Using RNA-seq-based transcriptome analysis for PEDV-infected Vero cells, researchers observed that significant changes in the mTOR signaling pathway occurred at different time points after viral infection, and this was further experimentally confirmed to promote virus infection." (PMID 35371109, 2022). "The second major type of pathways modulated by methotrexate treatment were related to the adaptive immune response, such as B cell receptor signaling, sphingolipid signaling pathway and mTOR signaling pathways, resulting in activation of B cells and T cells to counter viral infection." (PMID 36618412, 2022).
viral infection (continued). "The KEGG pathway enrichment analysis revealed that the predicted targets of DEmiRNAs were mainly enriched in the following signaling pathways: Wnt signaling pathway, mTOR signaling pathway, phagosome, and cysteine and methionine metabolism, which are related to virus infection." (PMID 36680059, 2022). "Increased literatures revealed that mTOR pathway plays an important role in virus infection." (PMID 35432224, 2022). "In addition, an adaptive immunological response to reactivations of latent viral infections would have to involve an activation of the mTOR pathway in several lymphocyte populations for effective lymphocyte proliferation and pathogen suppression." (PMID 33800846, 2021). "Overall, this study supports a beneficial role of metformin for viral hepatitis and also provides mechanistic evidence for the involvement of TSC1/mTOR in the regulation of T cell functions, providing a solid evidence for the therapeutic potential of metformin in viral infection." (PMID 33968030, 2021). "These inconsistencies in mTOR signalling in response to viral infection may be attributed to the duration and stage of infection and species-specific effects." (PMID 32130224, 2020). "However, further studies and clinical trials are needed to evaluate the effectiveness of mTOR inhibitors for protection against viral infections." (PMID 33013932, 2020). "We speculate that the increased sensitivity to mTOR inhibition during viral infection reflects the pleotropic effects of mTOR inhibition during the viral life cycle." (PMID 30677091, 2019). "Although mTOR inhibition offer the advantage of low nephrotoxicity, lower incidences of viral infection and beneficial effects on endothelial cell proliferation, various adverse events have been reported in transplant patients using mTOR based immunosuppression." (PMID 31239498, 2019). "However, further clinical data is still needed to understand the putative benefits of mTOR inhibitors against the development of certain types of cancers and viral infections in transplanted patients." (PMID 30510618, 2018). "As many viruses hijack the mTOR pathway to favor replication, using mTOR inhibitors as monotherapy or together with targeted antiviral drugs as a new strategy to treat viral infections may provide benefits in the clinic." (PMID 27231932, 2016). "As a metabolic sensor, mTOR activity is perturbed during viral infection." (PMID 26317997, 2015). "Other viral infection-related signaling pathways included eukaryotic initiation factor 2 (eIF2), mammalian target of rapamycin (mTOR), eukaryotic initiation factor 4 (eIF4)/ p70S6K, glucocorticoid receptor, NF-kappa B and innate cell-related pathways (natural killer cells and dendritic cells)." (PMID 26556803, 2015). "However, the cross talk between mTOR pathway and autophagy induction during viral infection is complex, and it has been reported that some viruses activate mTOR signalling." (PMID 24490870, 2014). "It is hypothesized that the HPV-host cell interaction stimulates the PI3K/Akt/mTOR pathway and inhibits autophagy, and in combination these events aid virus infection." (PMID 25202355, 2014). "Thus, targeting the mTOR pathway is a viable option to dampen an autoimmune response while leaving the immune system intact to fight viral infections." (PMID 24718491, 2014). "Regarding infectious complications associated with immunosuppression in organ transplantation, there is already early evidence that mTOR inhibitors might reduce the problem of some viral infections, including cytomegalovirus, human herpesvirus 8 and BK virus." (PMID 24565200, 2013). "When patients have been able to tolerate a switch from a CNI to an mTOR inhibitor in this time period, the benefits in the medium term are better allograft function, a lower incidence of cancer, and possibly a lower rate of viral infection." (PMID 24565283, 2013).
viral infection (continued). "In turn, if viral infections can be decreased, mTOR inhibitors could have an indirect impact on the development of post-transplant malignancies." (PMID 24565200, 2013). "Therefore, a better understanding of the interaction between the mTOR signaling pathway and orthoflavivirus infection may provide an important theoretical basis for the prevention and clinical treatment of viral infection." (PMID 40270809, 2025). "The mTOR signaling pathway is a central regulator of many cellular processes including cell metabolism, growth, and proliferation, but it is over-activated during viral infection, which could benefit viral replication." (PMID 37304876, 2023). "Moreover, the current ATP-competitive inhibitors are not limited to the treatment of tumors and cancers, but also have applications in central nervous system diseases, viral infections, inflammation, and other disorders, which lay the foundation for expanding the indications of mTOR inhibitors." (PMID 36014530, 2022). "During viral infection and liver damage different cell types, cell interaction and degree of cell activation coexist therefore, in this context, other molecular pathways may be involved in the regulation of mTOR." (PMID 33362215, 2020). "Having ruled out the two expected mechanisms (type I IFN and autophagy) by which mTORC1 could regulate viral infection, we addressed the mechanism of action using an unbiased approach, interrogating the effect of mTOR inhibition on the binding, entry, replication and/or spread of CHIKV." (PMID 26317997, 2015). "The interplay between AMPK, mTOR, and PI3K-Akt highlights the intricate metabolic rewiring during viral infections." (PMID 40723899, 2025). "Understanding the interplay between AMPK, mTOR, and PI3K-Akt in the context of viral infections provides valuable insights into host–virus interactions and potential therapeutic targets to restore metabolic balance and enhance antiviral immunity." (PMID 40723899, 2025). "To validate this, we utilized mTOR and CDK1 inhibitors, which mimicked the effects of viral infection, resulting in increased LARP1 binding to viral RNA." (PMID 40294010, 2025). "During acute viral infections, an early boost of both type I and II IFN-mediated signalling followed by PI3K/Akt/mTOR pathway activation is beneficial for GC-formation and for the generation of antigen-specific plasma cells." (PMID 39131331, 2024). "The relationship between viral infection and the PI3K/Akt/mTOR pathway, as well as its function in crucial physiological processes like as autophagy, apoptosis or the IFN induction cascade is known for other varicelloviruses." (PMID 37026095, 2023). "Many pieces of literature have demonstrated that after virus infection of host cells, it can regulate cellular glycolysis, fatty acid metabolism, and glutamine catabolism/glutaminolysis, the PI3K/Akt/mTOR pathway, c-myc, HIF-1α, and tumor formation." (PMID 36851737, 2023). "The phosphatidylinositol 3-kinases (PI3K)-Akt-mechanistic target of rapamycin (mTOR, PI3K-Akt-mTOR) is a cascade signaling pathway, which is often disrupted by viral infection." (PMID 36297385, 2022). "Recently, FBXW7 has also been shown to have multiple functions in virus infection via interacting with diverse host molecules such as SHP2, mTOR, and NS5B in immune responses." (PMID 35651754, 2022). "Several KEGG pathways were enriched in DMGs during heat exposure, including signaling networks, such as MAPK, mTOR, ErbB, PI3k/AKT and pathways related to hepatitis C and other viral infections that can be stimulated in response to heat stress." (PMID 34122501, 2021). "Mechanistic studies revealed the down-regulation of IFN-α expression mediated via mTOR signaling inhibition, where IFN-α plays a vital role in antibody response and protection against viral infection." (PMID 34157054, 2021).
viral infection (continued). "Tong and colleagues showed that the AKT/mTOR axis can be regulated by blocking phosphoinositide 3-kinase (PI3K) activation, thus sensitizing multiple cancer cell lines in vitro for viral infection." (PMID 34696274, 2021). "Here, we present the crosstalk of mTOR and RLR-signaling pathways by demonstrating the requirement of TFG for the interaction of TRAF3 and TBK1 with mTOR upon viral infection." (PMID 33411856, 2021). "Mechanistic targets of rapamycin (mTOR) and AMP-activated protein kinase (AMPK) are master regulators of metabolic gene expression, which affect cellular metabolism during viral infections." (PMID 30363715, 2018). "Other pathways of importance that were also differentially regulated were the JNK, mTOR, and GADD45 signaling pathways that are known to be altered during viral infections and with growth and development." (PMID 29164058, 2017). "Thus, our data suggest that LCMV infection elicits IL-22 expression from innate immune cells through the IL-23/PI3K/mTOR axis, and its production is essential for modulating antiviral T cell responses in both non-lymphoid and lymphoid tissues during acute and persistent viral infections." (PMID 28634408, 2017). "In dendritic cells, HIV-1 envelope (Env) glycoprotein induces activation of mTOR and S6K1, leading to inhibition of autophagy and increased virus infection." (PMID 27231932, 2016). "In case of both the viral infections, S 27 as well as DRDE-06, there were induction in the phosphorylation status of various Akt substrates like mTOR, 4EBP1 and S6K than that of the mock cells." (PMID 24959709, 2014). "Virus infection increased the protein levels of the autophagy markers ATG16L1 and Beclin-1 and the autophagy regulator mTOR." (PMID 23924832, 2013). "It is important to note that not all studies have reported a beneficialeffect of mTOR inhibitors in the context of viral infections." (PMID 40978637, 2025). "Modulation of the Ras-PI3K-Akt-mTOR signaling pathway, a crucial pathway involved in various cellular processes, including glycolysis, PPP, NADPH metabolism, and nucleotide synthesis, has been demonstrated in both viral infections and tumor progression." (PMID 40264189, 2025). "These non-canonical signaling pathways, including the activation of mitogen-activated protein kinases (MAPKs), mammalian target of rapamycin (mTOR), protein kinase C (PKC), IRF3, or NF-κB, can be activated by cellular stress (e.g., heat shock, DNA damage, oxidative stress) or viral infections." (PMID 40438119, 2025). "Viral infection activates various cellular responses in infected cells, including cellular stress responses such as unfolded protein response (UPR) and autophagy, following the inhibition of mTOR." (PMID 34206057, 2021). "Other trials have shown that e.g. an mTOR-(mechanistic target of rapamycin) inhibitor containing regimen can protect from single virus infections, but studies do not provide coinfection rates." (PMID 33376243, 2020). "This suggests that the activation of autophagy during viral infection is independent of mTOR inactivation and thus, by definition, noncanonical." (PMID 30608919, 2019). "Notably, in the mTOR pathway, there was a correlation with receptor genes leading to the PI3K-AKT pathway, lysosome, ribosome biogenesis, autophagy, and lipid biosynthesis, In the virus infection pathway, endocytosis and metabolic pathways were related." (PMID 39717902, 2024).